SHBG (sex hormone binding globulin)
Diseases named in the same sentence as SHBG in open-access papers (continued):
Sharing a sentence is not in itself a finding about the gene and the disease.
vitamin D deficiency (12 papers, 2016 to 2025). A nutritional condition produced by a deficiency of VITAMIN D in the diet, insufficient production of vitamin D in the skin, inadequate absorption of vitamin D from the diet, or abnormal conversion of vitamin D to its bioactive metabolites. "Participants with severe vitamin D deficiency (<25 nmol/L) had the lowest SHBG concentrations, with a median of 18.0 nmol/L and an interquartile range (IQR) of 14.1–56.2 nmol/L." (PMID 40868057, 2025). "It has been suggested that SHBG decreases with vitamin D deficiency, and free androgen levels increase and facilitate the basis for PCOS." (PMID 31423416, 2019). "This study aims to verify the extent to which a diversification of carbohydrates and fats intake in a diet, together with the reduction in vitamin D deficiency, impact the levels of hormones (testosterone, estradiol, cortisol) and Sex Hormone Binding Globulin (SHGB) in men doing strength training." (PMID 33139636, 2020). "Negative regulation of megalin by vitamin D suggests that vitamin D deficiency may lead to megalin upregulation and, subsequently, increased prostate import of SHBG-bound T. To test this hypothesis, we examined the relationship between these hormones in three cohorts of patients." (PMID 36875158, 2023). "As serum BPA, VDBP, 25(OH)D levels and the frequency of vitamin D deficiency were comparable between PCOS and control group, PCOS group women showed a negative correlation between their serum BPA and VDBP levels as well as SHBG levels." (PMID 36676087, 2023). "Vitamin D deficiency was associated with an imbalance in serum dehydroepiandrosterone (DHEA), sex hormone binding globulin (SHBG), testosterone (T), and free androgen index (FAI)." (PMID 31423416, 2019). "In the majority of human studies, Vitamin D deficiency has been associated with increased Sex Hormone Binding Globulin, but no change in circulating testosterone, resulting in a net decrease in biologically active, free testosterone." (PMID 36096748, 2022).
dementia (11 papers, 2012 to 2025). Loss of intellectual abilities interfering with an individual's social and occupational functions. "A large prospective study indicated that high serum level of SHBG, the primary plasma binding protein of sex hormones, was associated with an increased risk of all-cause dementia, including AD, among middle-aged to older women." (PMID 39974360, 2025). "Higher sex hormone–binding globulin (SHBG) levels increased the risk of dementia in one study (RR = 1.30, 95% CI = 1.10 to 1.70)." (PMID 37996855, 2023). "In the UK Biobank male population, higher SHBG was associated with higher all-cause mortality and with higher dementia risk." (PMID 35536887, 2022). "After excluding who experienced incident dementia event during the first 5 years of follow up, some linear associations of serum laboratory tests with the risk of dementia remained significant, such as SHBG, glucose, HbA1c, LDL, ALT, urate and vitamin D." (PMID 35927253, 2022). "SHBG, a secreted protein that plays a vital role in balancing bioactive sex hormones, has also demonstrated consistency with prior studies, in which higher levels of SHBG are associated with greater risks of dementia." (PMID 35927253, 2022). "Higher SHBG increased the risk of dementia or cognitive decline in male (N=6, RR=1.06, 95% CI=1.00-1.13, I2=24.8%), female (N=1, RR=1.30, 95% CI=1.10-1.70) and both genders (N=7, RR=1.10, 95% CI=1.01-1.20, I2=46.4%)." (PMID 33104518, 2020). "In conclusion, we found the endocrine profile of low TSH, high free-T4 and high SHBG was associated with an elevated risk of dementia or cognitive decline." (PMID 33104518, 2020). "Additionally, for every standard deviation increase in serum SHBG concentrations, the risk of developing dementia escalated by between 20 and 30% across a mean follow-up time of 5.2 years." (PMID 39974360, 2025). "Additionally, higher SHBG levels were linked to an elevated risk of dementia or cognitive decline (RR = 1.22, 95% CI = 1.06 to 1.39, pooled studies = 5, I2 = 0%)." (PMID 37996855, 2023). "In addition, higher SHBG levels were found to elevate the risk of dementia in men, consistent with a previous study." (PMID 37996855, 2023). "Higher SHBG may be associated with both cognitive decline in older men, and higher incidence of dementia and Alzheimer’s disease in middle-aged to older men." (PMID 35633431, 2022). "Thus in observational studies, testosterone concentrations are inversely, and SHBG concentrations directly, associated with risk of developing dementia and Alzheimer’s disease." (PMID 35633431, 2022). "We observed that CSF SHBG was inversely associated, albeit weakly, with cognitive function, which is in line with previous findings showing higher levels of serum SHBG associated with risk of dementia or cognitive decline." (PMID 34680117, 2021). "Therefore, bioactive sex hormone deficiency, reflected by levels of SHBG and testosterone, could potentially be used to predict dementia incidents." (PMID 35927253, 2022). "Increased risk of dementia or cognitive decline could be predicted by elevated blood concentrations of free-thyroxine (free-T4, RR = 1.06, p = 0.001) and sex hormone-binding globulin (SHBG, RR = 1.10, p = 0.025)." (PMID 33104518, 2020). "A study using the UK Biobank has revealed that there is a link between the development of dementia and AD in 159,411 men aged 50–73 years with lower testosterone and higher serum SHBG levels." (PMID 39974360, 2025). "Among the four laboratory tests under the “endocrine” category, there was evidence to show that high sex hormone-binding globulin level (SHBG, HR 1.004, 95% CI: 1.003–1.006, p = 8.6E-05) was associated with an increased risk of incident dementia." (PMID 35927253, 2022). "By contrast, men with lower SHBG concentrations had a lower incidence of dementia, and of dementia due to Alzheimer disease." (PMID 35633431, 2022).
dementia (continued). "Current evidence suggests the alterations of multiple blood molecules in HP axes, especially TSH, free-T4, and SHBG precede the incidence of dementia or cognitive decline." (PMID 33104518, 2020). "Increased levels of sex hormone-binding globulin (SHBG), which binds to sex steroids and reduces their bioactivity, have been linked to an increased risk of dementia in both men and women." (PMID 25859241, 2015). "However, other studies with direct measurement of endogenous estradiol (total or bioavailable estradiol (i.e., non-SHBG bound)) or estrone, showed inconclusive relationship between endogenous estrogen and cognitive function or dementia." (PMID 34977513, 2022). "In this study, we found the increased risk of dementia or cognitive decline could be predicted by a dropped blood concentration of TSH or DHEAS, as well as an elevated blood concentration of free-T4, SHBG, or IGFBP-2." (PMID 33104518, 2020). "Interestingly, high SHBG is generally accompanied by low TSH, high free-T4, and high estrogen, and they were all associated with a high risk of dementia or cognitive decline in our meta-analysis." (PMID 33104518, 2020). "Previous studies have shown that not only SHBG but also other hormones (e.g., estrogen, free thyroxin or thyroid-stimulating hormone) are associated with MMSE, suggesting that changes in the whole hypothalamic-pituitary (HP) axes may influence memory function and the risk of dementia or AD." (PMID 34680117, 2021). "The dementia risk of total-E2 in female could also be explained by the free hormone hypothesis, as we observed bioavailable E2 failed to predict the risk, while high SHBG (the predominant E2-binding protein in circulation) was associated with higher risk of dementia." (PMID 33104518, 2020).
erectile dysfunction (11 papers, 2014 to 2025). Persistent or recurrent inability to achieve or to maintain an erection during sexual activity. "Elevated SHBG reduces FT availability, and men with both low FT and high SHBG levels face the highest risk of erectile dysfunction." (PMID 39941224, 2025). "The aim of this current study was, therefore, to examine the long-term effects of weight loss with these diets on testosterone, SHBG, erectile dysfunction, sexual desire and LUTS, in overweight and obese men." (PMID 27584019, 2016). "Additionally, SHBG decreased lymphocyte count in both sexes (GCP = 0.39, p = 1.6e-07 for men, GCP = 0.42, p = 0.00014 for women), and in men SHBG decreased risk of erectile dysfunction (GCP = 0.42, p = 0.00032)." (PMID 36653534, 2023). "On the other hand, the evaluation of other markers, such as FSH, LH, prolactin, SHBG, and estradiol, is typically unnecessary in the routine work-up of erectile dysfunction, as elevated levels of these hormones are infrequent and have minimal impact on erectile function." (PMID 39941224, 2025). "FSH, LH, and SHBG showed an increase with each progressive severity of erectile dysfunction." (PMID 39941224, 2025). "Moreover, increasing insulin lowers the circulating amount of sex hormone-binding globulin (SHBG) and promotes free androgens, which constrains follicle formation resulting in irregular menses and impotency." (PMID 36407241, 2022). "The relationship between hormonal and biochemical parameters in the men showed that those with erectile dysfunction had statistically significantly lower TT concentration (p = 0.018), SHBG concentration (p = 0.026), and albumin concentration (p = 0.029) than those without dysfunction." (PMID 35805249, 2022). "As SHBG has a higher affinity for testosterone than for estradiol, thyroid dysfunction may disrupt the balance of available sex hormones in males, potentially leading to erectile dysfunction." (PMID 38689308, 2024). "Age correlates statistically significantly with both the severity of erectile dysfunction and the levels of total testosterone, free testosterone, LH, FSH, and SHBG." (PMID 39941224, 2025). "The main outcome measure was dynamic parameter changes of total testosterone, SHBG, FAI and erectile dysfunction." (PMID 30458009, 2018). "The infrequent occurrence and minimal impact of elevated FSH, LH, prolactin, SHBG, or estradiol levels in cases of erectile dysfunction do not support their routine evaluation." (PMID 39941224, 2025). "In contrast, LH, estradiol, SHBG, and prolactin do not demonstrate any statistical correlation with erectile dysfunction and should not be recommended as routine investigations." (PMID 39941224, 2025). "Although LH, PRL, and SHBG showed increases in median values across each severity group of erectile dysfunction, and estradiol demonstrated decreases, these changes did not statistically correlate with the severity of erectile dysfunction." (PMID 39941224, 2025).
Oligomenorrhea (11 papers, 2021 to 2025). Infrequent menses (less than 6 per year or more than 35 days between cycles). "Oligomenorrhea or an irregular menstrual cycle is reported to be associated with higher androgen levels and a lower level of SHBG." (PMID 35769085, 2022). "Moreover, they observed that high testosterone and free androgen index levels and low SHBG levels were associated with an increased OR for oligomenorrhea." (PMID 40150456, 2025). "In PCOS, although AMH levels are elevated, menstrual cycle abnormalities such as amenorrhea or oligomenorrhea are common, and SHBG tends to decrease." (PMID 38541016, 2024). "Clinical studies have also shown elevated total and free androgen levels and depressed SHBG in overweight/obese women with amenorrhea or oligomenorrhea." (PMID 36081684, 2022). "Associations were attenuated for total T with further adjustments for smoking, physical activity, menstrual status, oral contraceptive/hormone (OCHM) use, insulin level, oligomenorrhea, and age at menarche, but remained statistically significant for free T and SHBG." (PMID 38213908, 2024). "Moreover, a recent Greek study of 53 young women with T1DM demonstrated that increased androgen bioavailability due to decreased SHBG concentrations may result in delayed menarche, oligomenorrhea, and clinical hyperandrogenism." (PMID 38353886, 2024).
heart failure (10 papers, 2015 to 2026). Inability of the heart to pump blood at an adequate rate to meet tissue metabolic requirements. "An outcome-specific analysis revealed that higher dehydroepiandrosterone (DHEA) levels were linked to an increased risk of heart failure, while SHBG was associated with reduced cardiovascular mortality." (PMID 42238632, 2026). "Firstly, some studies have found that elevated serum SHBG levels are associated with a higher risk of cardiovascular disease, ischemic stroke, and heart failure in men and a higher risk of venous thromboembolism in women." (PMID 38152135, 2023). "Low SHBG levels correlated with measures of heart failure severity and were associated with a higher risk of cardiac death." (PMID 34335746, 2021). "Higher SHBG levels are associated with lower cardiovascular mortality, whereas higher DHEA levels correlate with increased heart failure risk." (PMID 42238632, 2026). "A third, older, MR study found increased risks of thromboembolism, myocardial infarction and heart failure in men, but it used a very limited genetic instrument for testosterone comprising of variants from only two loci (JMJD1C and SHBG)." (PMID 41131989, 2025).
myocardial infarction (10 papers, 2016 to 2025). Gross necrosis of the myocardium, as a result of interruption of the blood supply to the area, as in coronary thrombosis. "Prior researches suggested that men who have lower levels of sex hormone-binding globulin are more susceptible to myocardial infarction, with free testosterone levels potentially playing a role in the development of major adverse cardiovascular events." (PMID 37575123, 2023). "Sex hormone binding globulin was positively associated with thromboembolism and inversely associated with myocardial infarction, which makes any estimates using variants from the SHBG gene region open to pleiotropic effects and difficult to interpret." (PMID 30842065, 2019). "In contrast, we recently observed that low SHBG was associated with an increased risk of myocardial infarction in men in the UK Biobank, demonstrating that high SHBG is not simply a marker of general poor health in these men." (PMID 39373573, 2025).
Alzheimer disease (9 papers, 2017 to 2025). A progressive, neurodegenerative disease characterized by loss of function and death of nerve cells in several areas of the brain leading to loss of cognitive function such as memory and language. "Associations of genetically predicted female SHBG and testosterone in Alzheimer's disease using univariable MR in the UK Biobank." (PMID 39974360, 2025). "Associations of genetically predicted female SHBG and testosterone in Alzheimer's disease using multivariable MR (IVW)." (PMID 39974360, 2025). "Associations of genetically predicted male SHBG and testosterone in Alzheimer's disease using univariable MR in the UK Biobank." (PMID 39974360, 2025). "Hazard ratios with corresponding 95% confidence intervals of the association of SHBG levels with risk of Alzheimer’s disease according to strata of age, sex, and BMI." (PMID 32699184, 2020). "Although studies have demonstrated a correlation between sex hormone-related traits [such as sex hormone binding globulin (SHBG) and testosterone] and Alzheimer’s Disease (AD), the link remains uncertain due to the intricacies of AD pathology." (PMID 39974360, 2025). "It is also worth noting that similar inconsistencies on SHBG levels across studies analyzing blood from Alzheimer’s disease (AD) patients have also been observed." (PMID 34680117, 2021). "The mediation effect of SHBG on Alzheimer's disease via testosterone." (PMID 39974360, 2025). "In the Baltimore Longitudinal Study of Aging, men with a higher ratio of testosterone to SHBG at baseline performed better on tests of cognitive function, and were less likely to develop Alzheimer’s disease, during extended follow-up (10 and 19 years respectively)." (PMID 35633431, 2022). "Sex hormone-binding globulin (SHBG) in plasma was significantly elevated in subjects with Alzheimer’s disease (AD) than their matched controls, suggesting SHBG might be a circulating biomarker of AD." (PMID 32699184, 2020). "It was unclear whether sex hormone-binding globulin (SHBG) was a circulating biomarker of Alzheimer’s disease (AD)." (PMID 32699184, 2020). "Notably, we identified and quantified the mediating roles of 5 mediators between LTL and PCs, namely circulating leptin levels, sex hormone binding globulin levels, liver iron content, naïve CD4–CD8-T cell %T cell, and Alzheimer’s disease." (PMID 38831447, 2024). "Importantly, LTL remains an independent risk factor for PCs, suggesting that the impact of downstream mediators, including circulating leptin levels, sex hormone binding globulin levels, liver iron content, naïve CD4–CD8-T cell %T cell, and Alzheimer’s disease, on LTL is limited." (PMID 38831447, 2024).
Cirrhosis (9 papers, 2013 to 2023). A chronic disorder of the liver in which liver tissue becomes scarred and is partially replaced by regenerative nodules and fibrotic tissue resulting in loss of liver function. "Low testosterone levels stimulate the synthesis of sex-hormone-binding globulin (SHBG) in cirrhosis." (PMID 34205986, 2021). "Studies have shown an increase in SHBG levels and a reduced hepatic clearance of estradiol in patients with cirrhosis, producing variable effects on total testosterone levels." (PMID 34077443, 2021). "The disrupted sex hormone profile in cirrhosis may be brought on by metabolic issues with portosystemic hemodynamics (hypoestrogenism and elevated SHBG), or by the effects of drugs like spironolactone." (PMID 36730272, 2023). "No alternative cause of perturbed serum SHBG (eg, cirrhosis) was identified in any patient." (PMID 33901270, 2021).
hepatoma (9 papers, 2013 to 2026). "In vitro, we used co-cultures of human hepatocellular carcinoma cell line (HepG2) and human hepatic stellate cell line (LX-2) cells transfected using an SHBG expression vector vs. vehicle and treated with transforming growth factor beta 1 (TGF-β1)." (PMID 42278422, 2026). "SHBG and hepatocellular carcinoma: The protective role of SHBG also has potential implications for liver cancer development." (PMID 40625923, 2025). "In postmenopausal women, SHBG appears to inhibit NAFLD-induced hepatocellular carcinoma (HCC) through regulation of estrogen activity and inhibition of lipogenesis." (PMID 40625923, 2025). "Experimental studies using a human hepatoma cell line (HepG2) showed that SHBG expression is negatively affected by monosaccharides (glucose or fructose), insulin and androgens." (PMID 33139661, 2020). "In vitro studies using hepatoma cell lines demonstrate that high concentrations of insulin inhibit SHBG production." (PMID 33139661, 2020). "Insulin has been reported to inhibit SHBG production by hepatoma cells in vitro, suggesting that insulin may be an important regulating factor for SHBG in vivo." (PMID 30100880, 2018). "In vitro data on human hepatoma-culturedcells indicated that insulin-like growth factor 1 (IGF-1) may be a negativeregulator of SHBG synthesis.Upon aging, IGF-1 decreases, reducing the inhibitory effect on SHBG production inhepatocytes, which increases SHBG levels." (PMID 40857627, 2025). "Moreover, in vitro studies have shown that insulin might inhibit production of SHBG in human hepatoma cells, and in accordance with these findings an inhibitory effect of insulin on SHBG secretion has been reported." (PMID 23781314, 2013).